FBXW7-AS1 (FBXW7 antisense RNA 1)
Description:
Dual receptor for both endothelin-1 and the signal sequence of vascular endothelial growth factor A. Does not act as a receptor for angiotensin-2. Does not bind the VEGFA mature protein (By similarity). May play a role in angiogenesis with a significant role in cardiovascular and neural development (By similarity).
Synonyms: DEAR; DEspR
Gene: Long non-coding RNA gene on chromosome 4 (152,337,655 to 152,338,098, forward strand). Ensembl gene ENSG00000270751.
Subcellular location: Cell membrane
Diseases named in the same sentence as FBXW7-AS1 in open-access papers:
FBXW7-AS1 is named in the same sentence as 22 diseases in open-access papers, as found by Europe PMC text mining. Sharing a sentence is not in itself a finding about the gene and the disease.
FBXW7-AS1 shares sentences with these, for which no sentence is quoted: tumor (7 papers); acute respiratory distress syndrome (6); cancer (5); COVID-19 (4); pancreatic cancer (4); infection (3); glioblastoma (2); intracerebral hemorrhage (2); pancreatic ductal adenocarcinoma (2); acute kidney injury (1); acute respiratory failure (1); cerebrovascular disease (1); Encephalopathy (1); hemorrhage (1); hyperlipidemia (1); hypertension (1); mammary tumors (1); neutropenia (1); non-small cell lung carcinoma (1); rheumatoid arthritis (1); Stroke (1); triple-negative breast carcinoma (1).